INS (insulin)
Diseases named in the same sentence as INS in open-access papers (continued):
Sharing a sentence is not in itself a finding about the gene and the disease.
Hyperinsulinemia (continued). "The present study for the first time tried to understand the changes occurring in the insulin signaling pathway and the metabolic dysregulations occurring during the development of hyperinsulinemia and the effect of exercise on these signaling and metabolic pathways." (PMID 33708999, 2021). "At present, we are acutely aware of the deleterious effects of hyperinsulinism (endogenous or exogenous in diabetic patients to whom insulin is administered) with its consequent weight-gain and sodium reabsorption in the proximal tubule which increases the risk and incidence of heart failure." (PMID 34070103, 2021). "As a result, insulin enters the liver, which is the main target organ of insulin, at a much lower concentration than normal endogenous insulin which may give rise to hyperinsulinemia, weight gain, and hypoglycemic risks." (PMID 33066443, 2020). "Hyperinsulinemia-mediated islet and β-cell insulin/IGF-1 resistance, often overlooked, could be a key factor that contributes to β-cell decompensation." (PMID 32150819, 2020). "This binding occurs when insulin reaches high concentrations, as in compensatory hyperinsulinemia." (PMID 32103756, 2020). "Because insulin inhibits ketosis, the hyperinsulinemia in aged rats could be responsible for delayed keto-adaptation in aging." (PMID 32369441, 2020). "In addition, GIP potentiates insulin secretion from pancreatic β-cells as an incretin and thus plays an important role in hyperinsulinemia under HFD-feeding obese condition." (PMID 31977316, 2020). "Pharmacological approaches with diazoxide or the somatostatin analogue octreotide-LAR to suppress insulin secretion in humans, also support the view that hyperinsulinemia may have more of a primary role in MetS." (PMID 32630256, 2020). "Overall, these data suggest that FGF19 and FGF21 may have a modulatory role in lipid and insulin metabolism as shown by hyperinsulinemia and the lipid infusion." (PMID 33101202, 2020). "RI/NPH mainly contains the ingredients of insulin and protamine, and its anti-tumor effects may derive from protamine instead of insulin due to HCC-inducing exogenous hyperinsulinemia." (PMID 33382703, 2020). "SCGN’s ability to bind insulin might offer an explanation for the lower values in pregnancy compared to postpartum due to the pregnancy-related hyperinsulinemia." (PMID 32708966, 2020). "Insulin powerfully inhibits ketogenesis, therefore insulin receptor insensitivity and hyperinsulinemia could delay keto-adaptation." (PMID 32369441, 2020). "The low bone turnover associated with T1D is thought to be related to glycemic control, but it is unclear whether peripheral hyperinsulinemia due to dependence on exogenous insulin has an independent effect on suppressing bone turnover." (PMID 32995692, 2020). "It has been hypothesized that hyperinsulinemia may augment cancer cell growth and proliferation through insulin action via its receptor and the activation of IGF pathway." (PMID 33008076, 2020). "Whereas hepatic insulin clearance is regaining attention as the very first alteration leading to hyperinsulinemia, compensatory mechanisms that could emerge from the kidney are not well known." (PMID 32850773, 2020). "Interestingly, a TBC1D4 mutation (heterozygous premature stop mutation) was found in patients with both hyperinsulinemia and acanthosis nigrican, and it has been reported that this causes problems with GLUT4 translocation in response to insulin." (PMID 33255783, 2020). "It is well known that SeP is tightly related to glucose metabolism; specifically, high glucose concentration stimulates insulin secretion by the pancreas and SeP release by the liver that in turn exacerbates insulin secretion and hyperinsulinemia contributing to IR." (PMID 33266488, 2020).
Hyperinsulinemia (continued). "For instance, AKT-2, GSK-3β, GLUT1, and GLUT4 mRNA expression were upregulated in the hearts of hyperinsulinemic horses, suggesting that prolonged hyperinsulinemia induced an increase in insulin sensitivity in the heart, which could be cardioprotective." (PMID 32596266, 2020). "It is well-known that both insulin and CB are sympatho-modulators, and the prolonged exposure to hyperinsulinemia or tonic activations of CB may evoke SNS overactivation and metabolic dysfunction." (PMID 32698380, 2020). "Hyperinsulinemia, present in insulin resistant conditions, may worsen the prognosis of TC likely by potentiating IR-A/IGF2-dependent mitogenic functions." (PMID 33114365, 2020). "The present study demonstrated that the pharmacological blockade of CB1 improved hyperlipidemia (increased plasma TG and cholesterol levels), hyperinsulinemia (increased plasma insulin level), and increased inflammatory cytokine‐mediated NASH development in the obese db/db mice." (PMID 32798334, 2020). "Hyperinsulinemia can result from increased insulin secretion and/or reduced insulin clearance." (PMID 32860984, 2020). "In turn, this DON-induced hyperinsulinemia may contribute to liver steatosis since insulin is known to stimulate hepatic lipogenesis and to reduce β-oxidation." (PMID 32694515, 2020). "In light of the role of hyperinsulinemia in breast cancer growth and migration, the robust insulin-sensitizing anti-diabetic activity of MEDICA may translate to improved treatment of ErbB2 breast cancer in both diabetic and non-diabetic patients." (PMID 32695336, 2020). "Insulin regulates VEGF expression and hyperinsulinemia is linked to decreased VEGF production." (PMID 32153503, 2020). "However, the role of long-term exposure to high insulin (i.e., hyperinsulinemia) on β-cell function and mass is still unclear and very controversial." (PMID 32150819, 2020). "Hyperinsulinemia was also suggested to induce weight gain as insulin was found to inhibit the activity of adenosine monophosphate-activated protein kinase (AMPK), resulting in the enhancement of acetyl CoA carboxylase (ACC) activity, which promotes the biosynthesis of fatty acids." (PMID 32917200, 2020). "While we show diminished response to insulin in the liver, one can expect that chronic hyperinsulinemia would result in insulin resistance in various peripheral organs such as the adipose tissue, leading to the inability of peripheral tissues to perform insulin-mediated glucose uptake." (PMID 33345777, 2020). "It should be noted however that insulin levels in response to glucose ingestion were significantly higher in the obese mice, suggesting impaired glucose utilization in the obese mice, which required hyperinsulinemia to maintain glucose flux." (PMID 33099046, 2020). "Thus, our first conclusion is that hyperinsulinemia, observed during the ipGTT in AS mice, was due to an increased insulin secretion instead of alteration in insulin sensitivity/action at insulin-target tissues." (PMID 33324349, 2020). "Leprdb/db mice displayed hyperinsulinemia with serum insulin levels of 2586 μIU/ml." (PMID 31378829, 2020). "However, of the few studies that address insulin secretion in TS, some demonstrate hyperinsulinemia, and others suggest a decreased insulin secretion." (PMID 32849275, 2020). "On the other hand, a condition in which insulin is over-secreted is called hyperinsulinemia." (PMID 32552864, 2020). "Hyperinsulinemia has been shown to downregulate insulin action in skeletal muscle." (PMID 33658981, 2020). "Compared to a control population of mice that do develop sufficient hyperinsulinemia, mice with the pure secretory defect might thus exhibit superior insulin sensitivity in insulin tolerance tests." (PMID 33080873, 2020). "Since glucose and insulin are carried in the plasma, we were thus able to determine whether there was evidence of their redistribution with hyperinsulinemia." (PMID 31605649, 2020).
Hyperinsulinemia (continued). "Given that hyperinsulinemia is likely to cause drug resistance, metformin can lead to variations in the phosphorylation position of IRS‐1 to evoke insulin sensitivity; thus, this shift may be critical to metformin‐mediated sensitization of oxaliplatin." (PMID 32248666, 2020). "Peripheral insulin has been considered a negative regulator of pituitary GH gene expression and secretion because pituitary GH production is suppressed by the exposure of a pituitary cell line to insulin in vitro, peripheral injection of insulin into animals, and hyperinsulinemia in obese animals." (PMID 32644973, 2020). "Initially, in our earlier work, the HFD/STZ treated rats showed clear hyperglycemic condition (276.74 ± 6.03 mg blood glucose/dl) and hyperinsulinemia (36.84 ± 0.58 mg insulin/dL) when compared to the control group (95.72 ± 0.42 and 11.62 ± 0.25, respectively)." (PMID 33375437, 2020). "Transit hyperinsulinemia and enhanced glucose-induced insulin secretion by Ad-feed intake may accelerate hepatic and cardiac pathogenic progression." (PMID 33114772, 2020). "In clinical studies fasting insulin levels, or the fasting concentrations of C-peptide (a cleavage product of the insulin precursor that is released at equal concentrations to insulin) have been used to examine the links between hyperinsulinemia and cancer." (PMID 33604295, 2020). "Of note, downregulation of insulin signalling pathway may correlate with reported B. pertussis-induced hyperinsulinemia in human and mice." (PMID 32070192, 2020). "However, HFD mice develop hyperinsulinemia, and their insulin production is sufficient to maintain euglycemia, as indicated by their glycated hemoglobin levels." (PMID 32085589, 2020). "Hyperinsulinemia may also promote weight gain, since insulin overdose results in severe hypoglycaemia and polyphagia (excessive eating)." (PMID 33233346, 2020). "Therefore, improvements in blood sugar levels result in a slight decrease in serum insulin levels, which improves hyperinsulinemia." (PMID 33255783, 2020). "Building on this counterintuitive finding, we review the importance of pulsatile insulin secretion and highlight how normalizing glucose sensing in the beta cell during prediabetic hyperinsulinemia may restore pulsatility and improve glucose homeostasis." (PMID 32582035, 2020). "Furthermore, gestational T treatment leads to maternal hyperinsulinemia and disrupts insulin signaling in fetal metabolic tissues during critical periods of development that encompass pituitary gonadotroph differentiation." (PMID 33158439, 2020). "In this regard, a therapeutic target that simultaneously increases insulin sensitivity and suppresses hyperinsulinemia could be more effective and beneficial for the treatment of T2D." (PMID 32092075, 2020). "Insulin itself can create a positive feedback loop by activating ATF2 in this pathway solely or mediated by MAPK8 (preceded by MAP4K4) or PRKCE which can eventually lead to hyperinsulinemia." (PMID 32993798, 2020). "This represents a novel finding, as both basal and insulin-stimulated lipolysis were previously reported to be unchanged and highlights how essential the treatment with insulin is in a prolonged and persistent manner to maximize the effects of hyperinsulinemia." (PMID 32718202, 2020). "The impaired signaling of insulin demands increased concentrations of insulin (hyperinsulinemia)." (PMID 32962281, 2020). "Authors suggested that Hp is a marker of hyperinsulinemia and that insulin could modulate Hp production by the liver and white adipose tissue or both." (PMID 32695161, 2020). "Refined carbohydrates (refined starches and sugars) are rapidly absorbed into the bloodstream, inducing a high peak of insulin (hyperinsulinemia), The more a carbohydrate is refined, the larger is the glycaemic and insulinaemic responses which can be measured by the glycemic load." (PMID 32811458, 2020).
Hyperinsulinemia (continued). "Glucose infusion rate during hyperinsulinemia-euglycemia, which reflects whole-body insulin sensitivity, was comparable between genotypes during the whole clamp, steady state, and when normalized to plasma insulin levels at the end of the clamp." (PMID 32394396, 2020). "The presence of hyperinsulinemia together with increased tumor proliferation and glucose uptake observed in obese rodents, was reduced with therapies with insulin-lowering effects, such as an SGLT2 inhibitor or a liver-specific mitochondrial uncoupler of oxidative phosphorylation." (PMID 33604295, 2020). "However, they were exposed to hyperinsulinemia, plausibly explained by decreased insulin clearance as well as increased beta-cell function, in agreement with increased DI." (PMID 32785111, 2020). "Insulin is an anabolic hormone, and interaction with the cardiac insulin receptor as observed in congenital hyperinsulinism and in infants of diabetic mothers might explain the large weight and plethoric aspect of these patients." (PMID 31840185, 2020). "Examination of the Sur1-/- hyperinsulinism mouse model in the context of Prkar1a reduction, identified a distinct increase in not only fasting plasma glucose levels, but also a significant decrease in fasting insulin/glucose levels as well." (PMID 32735622, 2020). "Compared with NG piglets, male and female HG piglets revealed a significantly impaired glucose tolerance to a similar extent, associated with increased insulin secretion and fasting hyperinsulinemia in female but not male HG piglets." (PMID 31308048, 2019). "We also found that the postprandial plasma insulin responses improved 24 weeks after ezetimibe treatment in patients with MetS; these results were consistent with others showing ezetimibe reduced postprandial hyperinsulinemia." (PMID 30519809, 2019). "In brief, hyperinsulinemia in acanthosis nigricans patients not only can increase the binding of insulin and IGF-receptors, but also can reduce IGFBPs, thus increasing biologically active IGF-1, and resulting in the development of hyperkeratosis and papillomatosis." (PMID 31824416, 2019). "By contrast, hyperinsulinemia decreases insulin transport into the brain." (PMID 31551756, 2019). "Because there were only a few animals in this study with marked post-prandial hyperinsulinemia and the comparisons were underpowered, this hypothesis needs to be examined in a larger cohort of animals with insulin dysregulation." (PMID 31805097, 2019). "High circulating insulin may then trigger hyperinsulinemia in the ovaries, where insulin sensitivity remains normal despite peripheral insensitivity." (PMID 31367382, 2019). "Since obese-prediabetic (4-HCD) mice had elevated insulin and normalized adiponectin levels, and PIV responses had become similar to age-matched lean mice, we explored the possibility that hyperinsulinemia-driven insulin signalling was involved in the adaptive mechanism to normalize PIV." (PMID 30006585, 2019). "In addition, in the liver, there is a higher production of triglycerides and less insulin breakdown, leading to hyperinsulinemia." (PMID 31379754, 2019). "Therefore, iron interferes with the insulin prohibition of hepatic glucose secretion, and hepatic iron stores reduce the production of insulin leading to systemic hyperinsulinemia." (PMID 31470879, 2019). "Postnatal examinationhas also shownthat BPA may decrease insulin sensitivity and lead to hyperinsulinemia." (PMID 31217932, 2019). "Moreover, levels of RP11-151A6.4 were increased in PCOS patients with hyperinsulinemia (fasting insulin > 23 mIU/L; p < 0.0001)." (PMID 31507635, 2019). "The pathophysiological background of these clinical findings might include the procoagulant imbalance, the chronic exposure to high glucose levels and the effects of hyperinsulinemia, which are reflected, to a certain degree, to the use of insulin." (PMID 31138207, 2019).
Hyperinsulinemia (continued). "Evidence for a critical role for insulin in directly promoting tumor cell division is provided by data showing that while insulin promotes tumor cell division in vivo, pharmacologic agents which reverse hyperinsulinemia slow tumor growth unless exogenous insulin replacement is provided." (PMID 31188872, 2019). "The increase in glucagon secretion and subsequent stimulation of HGO can also stimulate insulin secretion, which could explain the hyperinsulinemia found in patients despite the inhibitory effect of SGAs on GSIS in the initial stages of the treatment." (PMID 31671770, 2019). "These IR-A-dependent metabolic effects are responsive to both IGF2 and insulin and might play a role in BC progression in obese and/or diabetic patients with hyperinsulinemia." (PMID 31480557, 2019). "A more physiological insulin replacement through closed loop may therefore help to prevent hyperinsulinemia and result in a lower insulin dose although more and longer observations will be needed to confirm this." (PMID 30849076, 2019). "The hPGH may also have the same diabetogenic effects as pituitary growth hormone such as hyperinsulinemia, decreased insulin-stimulated glucose uptake and glycogen synthesis, and impairment of the ability of insulin to suppress hepatic gluconeogenesis." (PMID 31828161, 2019). "Insulin may be related to the impact of a procoagulant imbalance, chronic exposure to high glucose levels, and direct effects of hyperinsulinemia." (PMID 30876424, 2019). "On this basis, it is tempting to speculate that the long-term consumption of extra-virgin olive oil might contribute to slow the progression of the inflammatory status, thus improving both insulin sensitivity and compensatory hyperinsulinemia also in PCOS." (PMID 31547562, 2019). "Metformin may slow these processes and improve healthspan by reducing hyperinsulinemia and improving peripheral tissue insulin sensitivity." (PMID 31555644, 2019). "Thus, we propose that the compensatory hyperinsulinemia exceeds the binding capacity of IR, allowing the insulin to bind to IGF-receptors." (PMID 31824416, 2019). "Thus, hyperinsulinemia can lead to a competition of insulin and Aβ for IDE, thereby increasing amyloid levels in the brain." (PMID 31293412, 2019). "Interestingly, catalpol has been reported to ameliorate the hyperinsulinemia in db/db mice, and potentiate insulin expression in the islet of diabetic rats induced by HFHG diet plus STZ injection (15 mg/kg)." (PMID 31514313, 2019). "Obese women show decreased insulin sensitivity determining persistent hyperinsulinemia, which may be involved in the pathogenesis of Polycystic Ovary Syndrome." (PMID 31231310, 2019). "The first hypothesis is the increase of circulating insulin level (hyperinsulinemia) that elevates the activity of GnRH neurons or pituitary responsiveness to GnRH." (PMID 30944702, 2019). "Overall, these in vitro studies suggest that the increase in basal insulin release and GSIS might explain the hyperinsulinemia associated with chronic treatment with SGAs in patients." (PMID 31671770, 2019). "In addition, systemic hyperinsulinemia secondary to impaired insulin sensitivity can occur during early DM." (PMID 31949435, 2019). "Notably, depending on the composition and timing of diet, beta cells respond to HFD feeding in mice with two actions–insulin compensation (which results in hyperinsulinemia) and/or insulin resistance." (PMID 31371780, 2019). "For instance, amino acids, such as leucine, phenylalanine, glutamine, and glutamate, induce pancreatic β-cell insulin secretion and may promote T2D via hyperinsulinemia, leading to pancreatic β-cell exhaustion." (PMID 31065046, 2019). "It is reasonable to assume that in an early hyperinsulinemia state such as prediabetes, symptoms are caused by a pseudo-insulin resistance state by impaired INSR trafficking rather than a genuine insensitivity of INSR signaling." (PMID 31658625, 2019).